SNORD113-3 (small nucleolar RNA, C/D box 113-3)
Synonyms: 14q(I-3)
Gene: Small nucleolar RNA gene on chromosome 14 (100,929,919 to 100,929,990, forward strand). Ensembl gene ENSG00000201700.
Gene Ontology:
Biological process: RNA processing
Cellular component: nucleolus
Homologues: Orthologues: chimpanzee SNORD113-3 (100% identical), macaque SNORD113-3 (99% identical), mouse Gm24564 (90% identical), rabbit SNORD113-3 (90% identical), guinea pig SNORD113-3 (89% identical), rat Snord113-3 (89% identical). Paralogues in human: SNORD113-9 (89% identical), SNORD113-8 (85% identical), SNORD113-6 (83% identical), SNORD113-7 (82% identical), SNORD113-4 (81% identical), SNORD113-5 (81% identical), SNORD113-2 (76% identical), SNORD114-10 (71% identical), SNORD114-12 (71% identical), SNORD114-18 (69% identical), SNORD114-2 (69% identical), SNORD113-1 (68% identical), and 26 more.